TENM1 (teneurin transmembrane protein 1)
Description:
Involved in neural development, regulating the establishment of proper connectivity within the nervous system. May function as a cellular signal transducer (By similarity). [Teneurin C-terminal-associated peptide]: Plays a role in the regulation of neuroplasticity in the limbic system. Mediates a rapid reorganization of actin- and tubulin-based cytoskeleton elements with an increase in dendritic arborization and spine density formation of neurons in the hippocampus and amygdala. Induces BDNF transcription inhibition in neurons. Activates the mitogen-activated protein (MAP) kinase 2 (MEK2) and extracellular signal-regulated kinase (ERK) cascade. Also acts as a bioactive neuroprotective peptide on limbic neurons of the brain and regulates stress-induced behavior: attenuates alkalosis-associated necrotic cell death and the effects of corticotropin-releasing factor (CRF) on c-fos/FOS induction and on the reinstatement of cocaine seeking (By similarity). [Ten-1 intracellular domain]: Induces gene transcription activation.
Synonyms: Ten-1; Ten-m1; ODZ1; TNM1; TEN1; ODZ3; TNM
Tractability: Antibody: its Gene Ontology location is reachable by antibodies, with high confidence; UniProt places it where antibodies can reach, with medium confidence; UniProt predicts a signal peptide or a membrane-spanning region; the Human Protein Atlas places it where antibodies can reach. PROTAC: its protein half-life has been measured.
Gene: Protein-coding gene on chromosome X (124,375,903 to 125,204,312, reverse strand). Ensembl gene ENSG00000009694.
Subcellular location: Cell membrane; Nucleus (Ten-1 intracellular domain); Nucleus speckle; Nucleus matrix; Cytoplasm, cytoskeleton; Nucleus (Teneurin C-terminal-associated peptide); Cytoplasm
Subcellular location (Human Protein Atlas): Nucleoplasm; Plasma membrane
Gene Ontology:
Molecular function: heparin binding; protein heterodimerization activity; protein homodimerization activity; signaling receptor binding
Biological process: axon guidance; immune response; negative regulation of cell population proliferation; nervous system development; positive regulation of actin filament polymerization; positive regulation of filopodium assembly; positive regulation of intracellular protein transport; positive regulation of MAP kinase activity; positive regulation of peptidyl-serine phosphorylation; regulation of transcription by RNA polymerase III; synaptic membrane adhesion; signal transduction
Cellular component: cytoplasm; cytoskeleton; endoplasmic reticulum; extracellular region; glutamatergic synapse; Golgi apparatus; neuron projection; nuclear matrix; nuclear speck; nucleus; perinuclear region of cytoplasm; plasma membrane; membrane
Homologues: Orthologues: chimpanzee TENM1 (99% identical), macaque TENM1 (99% identical), rabbit TENM1 (98% identical), pig TENM1 (98% identical), guinea pig TENM1 (97% identical), dog TENM1 (97% identical), rat Tenm1 (97% identical), mouse Tenm1 (97% identical), tropical clawed frog tenm1 (83% identical), zebrafish tenm1 (65% identical), Drosophila melanogaster Ten-m (32% identical), Drosophila melanogaster Ten-a (32% identical), and 2 more. Paralogues in human: TENM4 (64% identical), TENM3 (59% identical), TENM2 (57% identical), NAGPA (4% identical).
Diseases named in the same sentence as TENM1 in open-access papers:
TENM1 is named in the same sentence as 23 diseases in open-access papers, as found by Europe PMC text mining. Sharing a sentence is not in itself a finding about the gene and the disease. The quoted sentences say what the papers report.
glioblastoma (13 papers, 2018 to 2025). The most malignant astrocytic tumor (WHO grade IV). "TENM1 has been implicated in stemness and cancer cell differentiation both in glioblastoma and prostate cancer." (PMID 33652578, 2021). "However, data on the association between TENM1 deregulation and tumor progression are scarce and confined to a few tumor types, such as thyroid carcinoma, pituitary tumors, and glioblastoma." (PMID 40678018, 2025). "However, data on the association between TENM1 deregulation and tumor progression are scarce and confined to a few tumor types, such as thyroid carcinoma, pituitary tumor and glioblastoma." (PMID 33652578, 2021). "Upregulation of TENM1 contributes glioblastoma cell migration and invasion of the surrounding environment." (PMID 37542675, 2023). "Similar to the previous two genes, TENM1 can also play an important role in different types of cancer especially in the brain tumors such as prolactin pituitary tumor and glioblastoma." (PMID 36193505, 2022). "To date, an oncogenic role has been proposed for TENM1 in papillary thyroid carcinoma, prolactin pituitary tumor and glioblastoma." (PMID 33652578, 2021). "Indeed, TENM1 has been observed to be mainly concentrated in highly hypoxic tumor regions in surgical specimens from patients affected by glioblastoma." (PMID 33652578, 2021). "Interestingly, hypoxia has been identified as an extracellular activator of TENM1 expression in glioblastoma." (PMID 33652578, 2021). "Moreover, TENM1 mRNA up-regulation in response to hypoxia increases cell migration capacity in glioblastoma cells, while the blockade of TENM1 expression results in reduces hypoxia-induced glioblastoma cell migration." (PMID 33652578, 2021). "To date, a single report accomplished such assessment and could demonstrate that, in a subset of glioblastoma cells, methylation of TENM1 upstream sequences was indeed inversely correlated with transcript expression." (PMID 30618566, 2018). "Indeed, it has been demonstrated that TENM1 expression enables glioblastoma-derived cells to form neurospheres and to invade the surrounding microenvironment, while TENM1 down-regulation, through specific short hairpin RNA (shRNA), drastically halts glioblastoma cells’ invasive capacity." (PMID 33652578, 2021). "Consequently, TENM1-targeting could be proposed as a new strategy for glioblastoma therapy, as TENM1 overexpression is induced by hypoxia, and a hypoxic tumor microenvironment is associated with treatment resistance and poor prognosis." (PMID 33652578, 2021). "Moreover, reduced survival has been found in mice challenged with TENM1-overexpressing glioblastoma cells, and an inverse correlation between TENM1-positive cells and overall and progression-free survival has been found in samples derived from glioblastoma patients." (PMID 33652578, 2021). "Indeed, the absence of TENM1, achieved via gene deletion or down-regulation by small interfering RNA (siRNA), drastically reduces the invasive capacity of glioblastoma cells." (PMID 33652578, 2021).
papillary thyroid carcinoma (6 papers, 2019 to 2024). "Upregulation of ODZ1 (TENM1) expression has been associated with tumor progression and an invasive phenotype in papillary thyroid carcinoma." (PMID 35625843, 2022). "Recent data show that TENM1 is also up-regulated in a follicular variant of papillary thyroid cancer, and it is significantly more highly expressed and mutated in thyroid malignant nodules than in benign ones." (PMID 33652578, 2021). "TENM1 was overexpression in thyroid cancer and associated with thyroidal invasion and identified as potential marker of papillary thyroid carcinoma progress." (PMID 32164602, 2020). "The miR-486 down-regulation frequently observed in papillary thyroid carcinoma cells should thus justify the increased expression of TENM1." (PMID 33652578, 2021). "A gene expression study, performed on normal and papillary thyroid carcinoma tissues, identified TENM1 as one of the overexpressed genes in tumor, as compared to normal, tissues." (PMID 33652578, 2021). "Moreover, by comparing gene expression profiles during papillary thyroid carcinoma progression, Cheng and colleagues have found a correlation between the increase in TENM1 expression and disease progression from stage I to stage IV." (PMID 33652578, 2021). "Additionally, miR-486 inhibits cell proliferation, invasion, and migration by downregulating TENM1 expression and affecting the ERK and AKT signalling pathways and epithelial-to-mesenchymal transition in papillary thyroid carcinoma." (PMID 36618768, 2022).
thyroid cancer (5 papers, 2020 to 2025). "The possible oncogenic role of TENM1 in thyroid cancer progression is also supported by the fact that bioinformatics analyses and luciferase reporter assays have recently identified TENM1 as a direct functional target for miR-486 in this type of tumor." (PMID 33652578, 2021). "Multiple studies have shown that the expression of TENM1, which acts as a cell signal transducer in neurons, is highly positively correlated with the growth and invasion of PTC, and it is a potential biomarker for early diagnosis of thyroid cancer." (PMID 34221185, 2021).
schizophrenia (3 papers, 2018 to 2025). A major psychotic disorder characterized by abnormalities in the perception or expression of reality. "TENM1 (MO, NY) is associated with neural development and stress‐induced behaviour while HTR2A (NY) is a serotonin receptor associated with major depressive disorder, obsessive‐compulsive disorder, and schizophrenia." (PMID 41208600, 2025).
thymoma (2 papers, 2018 to 2021). A neoplasm arising from the epithelial cells of the thymus. "A third translocation involving C11orf73 (current gene name is HIKESHI) and TENM1 was detected in an advanced B3 thymoma." (PMID 30618566, 2018). "Earlier data not submitted to a repository might have been missed, as exemplified by the IGH/TENM2 and C11orf73/TENM1 translocations in MALT and B3 thymoma, respectively." (PMID 30618566, 2018).
X-linked intellectual disability (2 papers, 2023). An X-linked intellectual deficiency in which not enough information is known, reported or published to indicate whether a gene causes non-syndromic or syndromic presentations. "Finally, TENM1 has been implicated in X-linked intellectual disability." (PMID 37542675, 2023). "The TENM1 gene is broadly expressed in brain, prostate and 17 other tissues, is related to the fear of minor pain, and may be associated with X-linked intellectual disability." (PMID 38035272, 2023).
Anosmia (1 paper, 2021). An inability to perceive odors. "Recent data have demonstrated a role for TENM1 in the establishment of olfactory circuits; indeed, TENM1 deletion in mice affects their ability to detect odors and TENM1 mutations in humans are correlated with congenital anosmia." (PMID 33652578, 2021).
emotional dysregulation (1 paper, 2023). "We identified several molecular markers, including Dgkh, Arfgef3, Kcnh7, Grin2a, Tenm1 and Epha6, implicated in neurodevelopmental deficits and psychiatric conditions featuring impaired cognition and emotional dysregulation." (PMID 37542675, 2023).
infertile (1 paper, 2019). "HOXA10, EMX2, TENM1 mRNA and protein expression levels differ significantly in mid-secretory endometrium in infertile women with a Mullerian duct anomaly compared with controls." (PMID 31844537, 2019).
prostate carcinoma (1 paper, 2025). A carcinoma that arises from epithelial cells of the prostate gland. "Among the LE subtypes, LE-1 cells displayed progenitor-like characteristics by specifically expressing TENM1 (teneurin transmembrane protein 1), which has been implicated in prostate cancer differentiation." (PMID 41468516, 2025).
tumor (15 papers, 2015 to 2025). "The findings revealed that all selected genes except TENM1, which was downregulated, were overexpressed in EC tumor tissues." (PMID 39139739, 2024). "The increasing expression of TENM1 from the less to the more advanced tumor stages suggests its involvement in tumor progression and invasion, and pinpoints its potential role, not only as an oncogene, but also as a diagnostic biomarker." (PMID 33652578, 2021). "HBV integration in proximity to TENM1 was detected in a fourth adjacent normal specimen, while intragenic insertion at the TENM1 locus occurred in another tumor." (PMID 30618566, 2018). "Immunohistochemistry revealed that TENM1 protein levels were downregulated in EC tumor tissues." (PMID 39139739, 2024). "Immunohistochemistry results revealed that TENM1 protein levels were reduced in EC tumor tissues." (PMID 39139739, 2024). "This indicates that there is a potential oncogenic role of TENM1 in this tumor histotype." (PMID 33652578, 2021). "Interestingly, a single-cell analysis of circulating tumor cells, performed on a lung cancer patient, highlighted the presence of an acquired TENM1 single nucleotide variation in circulating tumor cells, whose function has not been elucidated." (PMID 33652578, 2021). "Our laboratory discovered the implication of TENM1, also known as ODZ1, in GBM cell migration in vitro and in tumor invasion using different in vivo models." (PMID 35625843, 2022). "We found that TENM1, FN1, and F12 are highly expressed in tumor tissue, while APOD and BTNL8 have a lower expression in tumor tissue." (PMID 34221185, 2021). "No known function for TENM-1 in TNBC, but if it serves a tumor suppressor role like what has been suggested for TENM2 in various type of tumors then that is consistent with the decreased expression in our FSCN1CON." (PMID 34959629, 2021).
cancer (10 papers, 2015 to 2025). A tumor composed of atypical neoplastic, often pleomorphic cells that invade other tissues. "The fact that TENM1 is a convergence point for various cancer-related signaling pathways might give us a new therapeutic opportunity for GBM treatment." (PMID 35625843, 2022). "In addition, luteolin treatment could significantly reduce the H3K9 acetylation on the promoter of TENM1, which is observed to be upregulated in several cancers." (PMID 26517526, 2015). "As observed for TENM1, the TENM2 gene is frequently altered in tumors, further hinting at its involvement in cancer development and progression." (PMID 33652578, 2021). "Moreover, even if not univocal, a correlation between TENM1 expression in different cancers and patients’ survival outcome can be observed." (PMID 33652578, 2021).
TENM1 also shares sentences with these, for which no sentence is quoted: glioma (3 papers); pituitary tumor (3); astrocytoma (1); brain cancer (1); brain tumors (1); breast tumor (1); cervical cancer (1); head and neck squamous cell carcinoma (1); major depressive disorder (1); ovarian serous cystadenocarcinoma (1); psychiatric diseases (1).